LRRC38 (leucine rich repeat containing 38)
Description:
Auxiliary protein of the large-conductance, voltage and calcium-activated potassium channel (BK alpha). Modulates gating properties by producing a marked shift in the BK channel's voltage dependence of activation in the hyperpolarizing direction, and in the absence of calcium.
Tractability: Antibody: UniProt places it where antibodies can reach, with medium confidence; UniProt predicts a signal peptide or a membrane-spanning region; its Gene Ontology location is reachable by antibodies, with medium confidence.
Gene: Protein-coding gene on chromosome 1 (13,474,973 to 13,514,003, reverse strand). Ensembl gene ENSG00000162494.
Subcellular location: Cell membrane
Gene Ontology:
Molecular function: potassium channel activator activity; transmembrane transporter binding; voltage-gated potassium channel activity
Biological process: positive regulation of voltage-gated potassium channel activity; potassium ion transmembrane transport
Cellular component: voltage-gated potassium channel complex; plasma membrane
Genetic constraint (gnomAD): Loss-of-function variants: 5 observed, 17.18 expected, observed/expected ratio (o/e) 0.29, 90% interval 0.15 to 0.61. The upper end of that interval is the gene's LOEUF score, 0.61, which puts it in group 2 of 6, group 1 being the genes least tolerant of losing a copy. Missense variants: 341 observed, 407.95 expected, observed/expected ratio (o/e) 0.84, 90% interval 0.76 to 0.91. Synonymous variants: 191 observed, 194.35 expected, observed/expected ratio (o/e) 0.98, 90% interval 0.87 to 1.11.
Homologues: Orthologues: chimpanzee LRRC38 (99% identical), macaque LRRC38 (97% identical), pig LRRC38 (93% identical), dog LRRC38 (92% identical), guinea pig LRRC38 (91% identical), mouse Lrrc38 (89% identical), rat Lrrc38 (89% identical), tropical clawed frog lrrc38 (64% identical), rabbit LRRC38 (62% identical), zebrafish lrrc38a (48% identical). Paralogues in human: LRFN2 (28% identical), LRFN3 (28% identical), LRFN5 (28% identical), SLIT1 (28% identical), SLIT2 (28% identical), LRFN4 (27% identical), SLIT3 (27% identical), LRFN1 (27% identical), LRRN2 (25% identical), TLR9 (25% identical), SLITRK4 (24% identical), SLITRK5 (24% identical), and 13 more.
Diseases named in the same sentence as LRRC38 in open-access papers:
LRRC38 is named in the same sentence as 4 diseases in open-access papers, as found by Europe PMC text mining. Sharing a sentence is not in itself a finding about the gene and the disease. The quoted sentences say what the papers report.
heart hypertrophy (1 paper, 2020). "The other SkM or SkM/heart LRRC genes with known functionality in muscle are LRRC38, a BK channel protein, and LRRC2, a gene previously associated with heart hypertrophy and mitochondria and downregulated in SkM upon stabilized weight-loss in human SkM." (PMID 34968235, 2020).
cancer (1 paper, 2022). A tumor composed of atypical neoplastic, often pleomorphic cells that invade other tissues. "Only the three remaining genes, KCNQ3, LRRC38 and RP1, were rarely reported in any cancer research, and thus show potential value for research in LUSC." (PMID 35962453, 2022).
cardiovascular diseases (1 paper, 2022). "On the contrary, FAM72A, KYAT1, LRRC38, and PTCHD4 had little or no known associations with cardiovascular diseases so far although they are moderately expressed in the heart and may have unidentified functions in AF." (PMID 36078037, 2022).
LRRC38 also shares sentences with these, for which no sentence is quoted: tumor (1 paper).